CD1D (CD1d molecule)
Description:
Antigen-presenting protein that binds self and non-self glycolipids and presents them to T-cell receptors on natural killer T-cells.
Synonyms: R3; R3G1
Tractability: Small molecule: a structure with a bound ligand is known; it has a high-quality binding pocket. Antibody: UniProt places it where antibodies can reach, with high confidence; its Gene Ontology location is reachable by antibodies, with high confidence; UniProt predicts a signal peptide or a membrane-spanning region.
Gene: Protein-coding gene on chromosome 1 (158,178,015 to 158,186,427, forward strand). Ensembl gene ENSG00000158473.
Subcellular location: Cell membrane; Basolateral cell membrane; Endosome membrane; Lysosome membrane; Endoplasmic reticulum membrane
Subcellular location (Human Protein Atlas): Endoplasmic reticulum
Pathways (Reactome):
Immune System: Immunoregulatory interactions between a Lymphoid and a non-Lymphoid cell
Gene Ontology:
Molecular function: cell adhesion molecule binding; exogenous lipid antigen binding; lipid antigen binding; protein binding; beta-2-microglobulin binding; endogenous lipid antigen binding; lipopeptide binding
Biological process: antigen processing and presentation, endogenous lipid antigen via MHC class Ib; positive regulation of T cell proliferation; antigen processing and presentation, exogenous lipid antigen via MHC class Ib; detection of bacterium; heterotypic cell-cell adhesion; immune response; positive regulation of innate immune response; positive regulation of T cell mediated cytotoxicity; T cell selection
Cellular component: basolateral plasma membrane; cell surface; cytoplasm; endoplasmic reticulum; endoplasmic reticulum membrane; endosome membrane; lysosomal membrane; lysosome; plasma membrane; external side of plasma membrane
Genetic constraint (gnomAD): Loss-of-function variants: 40 observed, 43.72 expected, observed/expected ratio (o/e) 0.92, 90% interval 0.71 to 1.19. The upper end of that interval is the gene's LOEUF score, 1.19, which puts it in group 5 of 6, group 1 being the genes least tolerant of losing a copy. Missense variants: 437 observed, 429.18 expected, observed/expected ratio (o/e) 1.02, 90% interval 0.94 to 1.1. Synonymous variants: 178 observed, 179.64 expected, observed/expected ratio (o/e) 0.99, 90% interval 0.88 to 1.12.
Homologues: Orthologues: chimpanzee CD1D (98% identical), macaque CD1D (93% identical), guinea pig CD1D (67% identical), pig CD1D (66% identical), rat Cd1d1 (64% identical), mouse Cd1d1 (61% identical), mouse Cd1d2 (47% identical), dog CD1D (44% identical), zebrafish mhc1lfa (20% identical), zebrafish mhc1lda (19% identical), zebrafish mhc1lja (18% identical), zebrafish si:dkey-52p2.5 (17% identical), and 5 more. Paralogues in human: CD1E (53% identical), CD1B (53% identical), CD1A (50% identical), CD1C (49% identical), HLA-F (24% identical), HLA-E (23% identical), HLA-B (23% identical), HLA-A (22% identical), HLA-G (22% identical), HLA-C (22% identical), MR1 (19% identical), FCGRT (19% identical), and 10 more.
Diseases named in the same sentence as CD1D in open-access papers:
CD1D is named in the same sentence as 217 diseases in open-access papers, as found by Europe PMC text mining. Sharing a sentence is not in itself a finding about the gene and the disease. The quoted sentences say what the papers report.
viral infection (29 papers, 2006 to 2025). "Subjects with iNKT cell deficiencies or reduced CD1d expression have intensified symptoms after viral infections." (PMID 40040714, 2025). "The protective and pathogenic role of CD1d-restricted T cells has been investigated in several animal models of persistent virus infections." (PMID 29616036, 2018). "Alterations in CD1d lipid presentation induced by viral infection appear linked to activation of pattern-recognition receptors, such as Toll-like receptors (TLRs)." (PMID 23202469, 2012). "Intriguingly, CD1d-restricted iNKT cells appear to play a critical role in anti-viral defense: increased susceptibility to disseminated viral infections is observed both in patients with iNKT cell deficiency as well as in CD1d- and iNKT cell-deficient mice." (PMID 23202469, 2012). "This is exemplified best by the observation that both patients with iNKT cell deficiency as well as CD1d- and iNKT cell-deficient mice are more susceptible to various viral infections." (PMID 23202469, 2012). "Recent reviews highlight how viral infections often regulate CD1d expression, thereby influencing iNKT cell-mediated immune responses." (PMID 40040714, 2025). "In agreement, lipodomics studies have shown that viral infections trigger endoplasmic reticulum (ER) stress which can in turn lead to the accumulation of certain CD1d-bound self-lipids that are recognised by the type I NKT TCR." (PMID 39355244, 2024). "Extensive research has shown that numerous viral infections also impact CD1d antigen presentation and thus type I NKT cell effector function, despite viruses not typically encoding lipid ligands." (PMID 39355244, 2024). "Type I NKT cells and CD1d antigen presentation molecules represent increasingly relevant players in host responses to viral infections." (PMID 39355244, 2024). "With such stark modulation of CD1d molecule expression and type I NKT cell function by viruses, the intricate relationship between the CD1d-iNKT cell axis and viral infections is evident." (PMID 39355244, 2024). "During viral infections, iNKT cells need two stimulation signals from antigen presenting cells to become activated: recognition of self‐lipid‐loaded CD1d by their TCR, and stimulation with type one interferon." (PMID 37102646, 2023). "Virus infection promoted the upregulation of CD1d and CD86 on monocytes, and the CD1dhighCD86high monocytes were easier to be targeted and eliminated by AlloHSC-iNKT cells, resulting in a residual CD1dlowCD86low population." (PMID 35313965, 2022). "Mechanistically, host cell-released lipids during viral infection are presented by lung infiltrating CD1d+ B-1a cells to activate IL-17A production in γδ T cells via γδTCR-mediated IRF4-dependent transcription." (PMID 33772013, 2021). "In contrast, we previously reported that elevated ERK activation enhances CD1d-mediated antigen presentation during a viral infection by regulating intracellular CD1d trafficking." (PMID 29354122, 2017). "Several studies suggested the possible involvement of the pro-inflammatory signals that enhance CD1d-dependent self-lipid presentation, self-lipids “alteration” during viral infection, or the inhibition of enzymes that degrade endogenous lipid antigens." (PMID 26257744, 2015). "The presence of CD1d:self-lipid complexes is also often required for cytokine-mediated stimulation of iNKT cells during bacterial and viral infections." (PMID 26697007, 2015). "In this review, we summarize the current information on the role of iNKT cells, CD1d, and lipid antigens during viral infection." (PMID 26257744, 2015). "In actual viral infections, CD1d was upregulated in cardiac endothelial cells in mice infected with coxsackievirus B3 virus, hepatocytes from HCV infected patients, and in monocytes from DENV-infected patients." (PMID 26257744, 2015). "Another piece of evidence supporting a CD1d-dependent response during viral infection is the finding that some viruses downregulate surface CD1d." (PMID 26257744, 2015).
viral infection (continued). "The earliest reports of viral-infection-induced CD1d downregulation were from lymphocytic choriomeningitis virus (LCMV), vaccinia virus (VV), and vesicular stomatitis virus (VSV) infections." (PMID 26257744, 2015). "Limited evidence is available regarding CD1d-dependent endogenous lipid presentation to iNKT cells during viral infection." (PMID 26257744, 2015). "The identity of physiologically relevant, stimulatory lipid antigens presented by CD1d in the context of viral infection remains, at this time, incompletely understood." (PMID 23202469, 2012). "In conclusion, TLR-mediated recognition of viral infection leads to altered lipid presentation by CD1d molecules, thereby affecting the activation of iNKT cells." (PMID 23202469, 2012). "Note that there was a slight decrease in CD1d presentation due to lentiviral transduction alone, consistent with the results of others that viral infection itself can modestly impact CD1d presentation." (PMID 21802320, 2011). "Overall, we suggest that the CD1d-iNKT cell axis may hold greater gravity within viral infections than what was previously appreciated." (PMID 39355244, 2024). "Exacerbated symptoms following viral infection have been particularly observed in individuals with decreased CD1d molecule expression or type I NKT cell deficiencies, underscoring the importance of the CD1d-iNKT cell axis in controlling viral infections." (PMID 39355244, 2024). "It is thus evident that the CD1d-iNKT cell axis instructs a profound immune response which may be necessary in defending the host from an aggravated viral infection." (PMID 39355244, 2024). "The strength of the CD1d agonist would lie in the rapid responses to unknown emerging viral infections when vaccines and other virus-specific approaches are still under investigation." (PMID 37402814, 2023). "However, viral infections can lead to upregulation of CD1d by triggering toll-like receptors (TLRs)." (PMID 29973936, 2018). "Increased iNKT cell activation during persistent virus infections may also result from viral blockers inhibiting the autophagic machinery, which downregulates iNKT cell responses through CD1d internalization." (PMID 29616036, 2018). "Because dNKT cells are also reactive to CD1d-loaded lipids, the up- or downregulation of CD1d in viral infection could also affect dNKT cells." (PMID 26257744, 2015). "The downregulation of CD1d can diminish the iNKT cell response and worsen the outcome of several viral infections, suggesting that iNKT cells might be a significant player in combating against certain viral infections." (PMID 26257744, 2015). "Importantly, potential CD1d-loaded lipid antigens as iNKT cell ligands in viral infection will be discussed and proposed." (PMID 26257744, 2015). "The upregulation of CD1d in response to viral danger signals could therefore be a possible mechanism for initiating the iNKT cell response to the viral infection." (PMID 26257744, 2015). "Pro-inflammatory signals produced during viral infection may stimulate iNKT cells through enhanced CD1d-dependent endogenous lipid presentation." (PMID 26257744, 2015). "Cytokines may activate iNKT cells during infections from influenza and murine cytomegalovirus, although CD1d-dependent activation is evident in other viral infections." (PMID 26257744, 2015). "Altogether, the discrepancy in the CD1d requirement in viral infections may support a notion that different viruses may trigger distinct pathways to activate iNKT cells." (PMID 25615690, 2015). "Moreover, investigating how viral infection affects iNKT cell activation will yield further understanding of conventional CD1d-mediated lipid presentation." (PMID 23202469, 2012). "Therefore, the iNKT cell stimulatory lipids presented by CD1d during viral infection must be of host cell origin." (PMID 23202469, 2012).
viral infection (continued). "Whereas a number of bacteria-derived lipid antigens have been identified that are capable of eliciting an iNKT cell response when presented as lipid/CD1d complexes, the identity of antigenic lipids presented during viral infection remains currently unknown." (PMID 23202469, 2012). "The regulation of MHC antigen processing and presentation during viral infection involves four genes: AP3B1, B2M, CD1A, and CD1D." (PMID 41155393, 2025). "The importance of CD1d expression and type I NKT cell activity within viral infections has also been supported by studies using murine models." (PMID 39355244, 2024). "In a striking contrast to B cell activation by glycolipid antigens, CD1d-mediated interactions between B cells and NKT cells are dispensable during viral infection." (PMID 29249358, 2018). "Thus, viral infections could lead to activation of iNKT cells in a CD1d-dependent manner." (PMID 29973936, 2018). "Moreover, some viruses downregulate CD1d expression, presumably to evade iNKT cell recognition, suggesting that CD1d-bound endogenous lipid antigens might be involved in iNKT cell response during viral infection." (PMID 26257744, 2015). "Together, these findings demonstrate the importance of CD1d-dependent iNKT cell activation in the cellular response to viral infection even though viruses contain no known exogenous lipid antigens." (PMID 26257744, 2015). "While the significance of CD1d-dependent iNKT cell activation in viral infection remains controversial, APC stimulation by viral toll-like receptor (TLR) agonists has been shown to lead to a shift in cellular lipid metabolism toward antigenic lipids as well as CD1d-dependent iNKT cell activation." (PMID 26257744, 2015). "Since viruses do not contain viral lipid antigens, it is postulated that viral infection may alter endogenous lipid presented on CD1d and activate iNKT cells with or without help from cytokines." (PMID 24945350, 2014). "gB was essential, but not sufficient, for CD1d downregulation during viral infection." (PMID 23202469, 2012). "Interestingly, CD1d−/− mice also displayed a significant reduction in germinal center formation when infected with the vaccinia virus Western Reserve strain, suggesting that the ability of NKT cells to promote B cell responses is a general feature of viral infections." (PMID 29249358, 2018). "For instance, NKT activated in response to α-GalCer modulate B cell response in a CD1d-TCR dependent manner, while during viral infection, activated NKT cells can influence B cell responses in a non-cognate fashion via the production of cytokines such as IL-419." (PMID 35260653, 2022). "In infected B6, Kb−/−xDb−/−, and Kb−/−xDb−/−xCD1d−/− mice, however, the percentages and absolute numbers of both CD4 and CD8 T cells were similar, indicating that viral infection stimulated a massive expansion of CD8 T cells in mice lacking the Class Ia and CD1d molecules." (PMID 16733540, 2006).
myeloma (27 papers, 2009 to 2025). "Engagement of CD1d by anti-CD1d monoclonal antibodies induces cell death of myeloma cell lines associated with overexpression of proapoptotic Bax and mitochondrial membrane potential loss." (PMID 38579449, 2024). "A similar scenario exists for multiple myeloma and B-cell lymphoma, since CD1d is downregulated and associated with poor outcomes in contrast to higher CD1d expression levels in PBMCs from healthy individuals." (PMID 34335558, 2021). "Several studies showed that premalignant and early myeloma tumor cells had significantly elevated CD1d levels." (PMID 38672732, 2024). "As the disease progressed, CD1d expression decreased and finally vanished completely, which was detrimental to myeloma cell survival." (PMID 38672732, 2024). "CD1d is highly expressed in premalignant and early myeloma, but its expression decreases with disease progression." (PMID 38579449, 2024). "These HSC-derived iNKT cells effectively suppressed multiple myeloma cells in a xenograft model in a CD1d-dependent manner." (PMID 36830717, 2023). "Surface CD1d expression is lost or downregulated in the majority of solid tumours and in some cancers -such as multiple myeloma- CD1d downregulation correlates with increased metastatic potential and disease progression." (PMID 36344546, 2022). "Premalignant and early-stage myeloma cells show high expression of CD1d, which decreases in the advanced stages." (PMID 32231116, 2020). "NKT cells can recognize and kill CD1d-expressing tumors such as lymphoma, early myeloma, prostate cancer, medulloblastoma and myeloid leukemia." (PMID 31387637, 2019). "With disease progression CD1d expression levels were down-regulated and eventually lost altogether in advanced MM patients and in most of the studied myeloma cell lines, leading to a reduction in survival." (PMID 26895468, 2016). "b) In comparison to the myeloma produced CD1d-dimers, Tween20 showed lower efficacy in αGC loading than Tyloxapol which was essentially as effective as Triton X100." (PMID 26599805, 2015). "It has been described previously that the expression of CD1d molecules is significantly downregulated in patients with advanced stages of MM compared to healthy controls, MGUS and early myeloma patients, suggesting a reason for loss of iNKT activity." (PMID 23741460, 2013). "Along this line, NKT-mediated killing of early stage myeloma cells which express CD1d molecules is lost upon transition to advanced myeloma stage and subsequent loss of CD1d expression." (PMID 24212972, 2011). "For example, blood samples from human multiple myeloma patients were recently reported to contain elevated frequencies of LPC-reactive CD1d-restricted T cells." (PMID 19859526, 2009). "Moreover, CD1d-specific camelid-derived VHHs also induced apoptosis of CD1d-expressing B lymphoblasts and multiple myeloma cells." (PMID 38579449, 2024). "Myeloma cells that express CD1d are sensitive to lysis by iNKT cells, but the CD1d expression is almost totally lost in the advanced stages of MM and in the myeloma cell lines as part of the immune evasion mechanisms of this cancer by contributing to iNKT cell anergy in MM." (PMID 35756630, 2022). "Even though so far no clear evidence demonstrates that the involvement of CD1d-lipid antigens in tumor cell recognition by γδ T cells; however, CD1d is found to be expressed on multiple cancers, such as lymphomas, early myeloma, myeloid leukemias, medulloblastoma, and prostate cancers." (PMID 32413966, 2020). "Other nanobodies could block the NKT TCR-CD1d interaction or induce CD1d+ cell apoptosis, with a potential use for CD1d+ B lymphoblasts or multiple myelomas." (PMID 31544819, 2019). "Tumors arising from certain CD1d+ cell types, such as some B cell lymphomas, commonly retain CD1d expression, though levels may vary with tumor stage, for example, declining during progression in multiple myeloma." (PMID 41000376, 2025).